TTLL1 (TTL family tubulin polyglutamylase complex subunit L1)
Description:
Catalytic subunit of a polyglutamylase complex which modifies tubulin, generating side chains of glutamate on the gamma-carboxyl group of specific glutamate residues within the C-terminal tail of tubulin. Probably involved in the side-chain elongation step of the polyglutamylation reaction rather than the initiation step. Modifies both alpha- and beta-tubulins with a preference for the alpha-tail. Unlike most polyglutamylases of the tubulin--tyrosine ligase family, only displays a catalytic activity when in complex with other proteins as it is most likely lacking domains important for autonomous activity. Part of the neuronal tubulin polyglutamylase complex. Mediates cilia and flagella polyglutamylation which is essential for their biogenesis and motility. Involved in respiratory motile cilia function through the regulation of beating asymmetry. Essential for sperm flagella biogenesis, motility and male fertility. Involved in KLF4 glutamylation which impedes its ubiquitination, thereby leading to somatic cell reprogramming, pluripotency maintenance and embryogenesis.
Synonyms: PGs3; C22orf7; TPGS3; HS323M22B
Tractability: Antibody: its Gene Ontology location is reachable by antibodies, with medium confidence. PROTAC: ubiquitination databases record sites on it; its protein half-life has been measured.
Gene: Protein-coding gene on chromosome 22 (43,039,516 to 43,089,427, reverse strand). Ensembl gene ENSG00000100271.
Subcellular location: Cytoplasm, cytoskeleton; Cytoplasm, cytoskeleton, cilium basal body; Cytoplasm, cytoskeleton, cilium axoneme; Cell projection, cilium, flagellum
Pathways (Reactome):
Metabolism of proteins: Carboxyterminal post-translational modifications of tubulin
Gene Ontology:
Molecular function: tubulin-glutamic acid ligase activity; protein-glutamic acid ligase activity, elongating; tubulin binding
Biological process: microtubule cytoskeleton organization; protein polyglutamylation; sperm axoneme assembly
Cellular component: microtubule; catalytic complex; ciliary basal body; axoneme; cytoskeleton; motile cilium
Genetic constraint (gnomAD): Loss-of-function variants: 34 observed, 50.93 expected, observed/expected ratio (o/e) 0.67, 90% interval 0.51 to 0.89. The upper end of that interval is the gene's LOEUF score, 0.89, which puts it in group 3 of 6, group 1 being the genes least tolerant of losing a copy. Missense variants: 488 observed, 554.97 expected, observed/expected ratio (o/e) 0.88, 90% interval 0.82 to 0.95. Synonymous variants: 225 observed, 219.36 expected, observed/expected ratio (o/e) 1.03, 90% interval 0.92 to 1.15.
Homologues: Orthologues: macaque TTLL1 (99% identical), rat Ttll1 (97% identical), mouse Ttll1 (97% identical), guinea pig TTLL1 (96% identical), rabbit TTLL1 (95% identical), dog TTLL1 (91% identical), pig TTLL1 (90% identical), chimpanzee TTLL1 (88% identical), tropical clawed frog ttll1 (85% identical), zebrafish ttll1 (84% identical), Drosophila melanogaster TTLL1B (64% identical), Drosophila melanogaster TTLL1A (51% identical). Paralogues in human: TTLL9 (41% identical), TTLL13 (29% identical), TTLL6 (29% identical), TTLL2 (28% identical), TTLL4 (27% identical), TTLL11 (26% identical), TTLL3 (25% identical), TTLL7 (24% identical), TTLL10 (21% identical), TTLL8 (21% identical), TTLL12 (17% identical), KPRP (10% identical).
Diseases named in the same sentence as TTLL1 in open-access papers:
TTLL1 is named in the same sentence as 17 diseases in open-access papers, as found by Europe PMC text mining. Sharing a sentence is not in itself a finding about the gene and the disease. The quoted sentences say what the papers report.
bovine tuberculosis (1 paper, 2022). "Interestingly, TTLL1 is repressed in bovine PBMCs after vaccination against bovine tuberculosis (bTB), supporting a more effective immune response against tuberculosis, with a yet unclear relationship." (PMID 35743950, 2022).
cardiac hypertrophy (1 paper, 2017). "Expression of TTLL1 gene has been found to be significantly decreased in the case of pathological hypertrophy (PAH)." (PMID 28861005, 2017). "Since previous findings from our lab have reported that CSN8-CKO mice also developed cardiac hypertrophy, we sought to determine the effect of CSN8 deficiency on TTLL1 gene expression." (PMID 28861005, 2017).
chronic sinusitis (1 paper, 2015). "Moreover TTLL1 deficiency resulted in chronic sinusitis and abnormal development of spermatid flagella in mice." (PMID 26430897, 2015).
ciliary dyskinesia (1 paper, 2015). "Because impaired mucociliary clearance seemed to be the cause of the accumulated mucus, we examined whether ciliary dyskinesia in the nasal epithelium of the Ttll1−/− mice resulted in impaired nasal mucociliary clearance." (PMID 26581078, 2015).
epilepsy (1 paper, 2023). A brain disorder characterized by episodes of abnormally increased neuronal discharge resulting in transient episodes of sensory or motor neurological dysfunction, or psychic dysfunction. "The result suggests that loss of Ttll1 and Ttll7 genes was associated with the antiseizure function or prevention of epilepsy." (PMID 37238654, 2023). "In 135 min of observation, Ttll1(Het)/Ttll7(Homo) mice had a significantly longer duration of obvious epilepsy-like symptoms (highest score) than WT mice (WT 3.23 ± 0.15, 7KO 3.75 ± 0.10, t = 5.17, p = 0.0066, unpaired t test)." (PMID 37238654, 2023).
male infertility (1 paper, 2022). The inability of the male to effect fertilization of an ovum after a specified period of unprotected intercourse. "Given that depletion of Ttll1 or Ttll4 ameliorated neuronal degeneration in pcd mice, we assessed whether knocking out Ttll1 or Ttll4 could also rescue male infertility." (PMID 35404950, 2022). "However, only loss of Ttll1 but not Ttll4 corrected the excessive tubulin polyglutamylation in pcd cerebellum and loss of none of the Ttlls rescued male infertility." (PMID 35404950, 2022).
neuritis (1 paper, 2023). A neuropathy arising from inflammation of one or more nerves. "In TTLL1 mutant mice, the targeting of KIF1A, a subfamily of kinesin-3 in neuritis, was impaired, but the distribution of KIF3A (kinesin-2) and KIF5 (kinesin-1) was not altered." (PMID 37321451, 2023).
rhinosinusitis (1 paper, 2015). "As previously reported, Ttll1−/− mice were affected with rhinosinusitis." (PMID 26581078, 2015).
scoliosis (1 paper, 2023). A congenital or acquired spinal deformity characterized by lateral curvature of the spine. "Among the genes that have been confirmed to be involved in the development of scoliosis in humans (TBX6, FGF3, LBX1, POC5, TTLL1) and vertebrates (Kif6 and Ptk), several are ciliary genes." (PMID 37239471, 2023).
neurological diseases (1 paper, 2023). "Ttll1 and Ttll7 can be potential therapeutic target genes for neurological diseases through the investigation of drugs modulating tubulin polyglutamylation levels." (PMID 37238654, 2023).
TTLL1 also shares sentences with these, for which no sentence is quoted: brain disorder (1 paper); cancer (1); dyslexia (1); hypertrophy (1); infection (1); neuroblastoma (1); tuberculosis (1).